MGMT (O-6-methylguanine-DNA methyltransferase)
Diseases named in the same sentence as MGMT in open-access papers (continued):
Sharing a sentence is not in itself a finding about the gene and the disease.
pituitary tumor (13 papers, 2014 to 2025). A benign or malignant neoplasm affecting the pituitary gland. "Low immunoexpression of MGMT by pituitary tumors has been associated with high response rates to temozolomide." (PMID 30020466, 2019). "In pituitary tumors, low-level immunoexpression of MGMT has been associated with a positive response to TMZ, and high MGMT expression, with lack of response." (PMID 29963012, 2018). "In pituitary tumors, including invasive corticotroph tumors, low MGMT expression was also more frequent in aggressive compared to non-aggressive subtypes." (PMID 40257628, 2025). "For this reason, the routine determination of MGMT status in all aggressive pituitary tumours by immunochemistry is recommended." (PMID 34681905, 2021). "Differences in methodology of MGMT immunostaining and assessment however, complicate the comparison of existing studies thus the clinical value of MGMT expression for pituitary tumours." (PMID 29344904, 2018). "Contrary to GBM, in pituitary tumors, immunohistochemistry analysis of MGMT has been frequently used, and tumors with low MGMT immunoexpression have generally had a better response to treatment." (PMID 29963012, 2018). "They reported the results that eleven out of 88 PA samples (13%) had low MGMT expression, and that prolactinomas were more likely to have low MGMT expression compared with other pituitary tumor subtypes." (PMID 25027022, 2014). "McCormack group demonstrated that low MGMT expression and MGMT promoter methylation were found in the pituitary tumor of the patient who responded to TMZ, high MGMT expression was seen in the patient demonstrating a poor response to TMZ." (PMID 25027022, 2014). "Interestingly, pituitary tumors with high MGMT display a different set of activated genes than those with low MGMT expression." (PMID 40257628, 2025). "Hence, pituitary tumors showing low MGMT and low MPG expression would be highly responsive to TMZ, because unrepaired O6-MeG, N7-Meg, and N3-MeA adducts, would trigger cytotoxicity by different ways." (PMID 29963012, 2018). "Therefore, MSH6 and MGMT immunoexpression analysis has been proposed in the morphologic study of pituitary tumors." (PMID 29963012, 2018). "MGMT expression as assessed by immunohistochemistry may predict response to temozolomide therapy in patients with aggressive pituitary tumors." (PMID 25027022, 2014). "This suggests that MGMT expression, yet not MGMT promoter methylation, can serve as a predictive factor for the response to treatment in aggressive pituitary tumors, including APRL." (PMID 37529607, 2023). "In pituitary tumors, the expression of MGMT but not methylated MGMT promoter can predict the response to temozolomide treatment." (PMID 31726770, 2019). "In pituitary tumors, MGMT promoter methylation does not always correlate with MGMT protein expression, and other yet unraveled regulatory mechanisms may contribute as well." (PMID 40257628, 2025). "Together, MGMT promoter methylation is likely to explain low-level MGMT expression in some, but not all, pituitary tumors, as further regulation may occur at the transcriptional, post transcriptional, or translational levels." (PMID 26400193, 2015).
neuroblastoma (12 papers, 2004 to 2025). Neuroblastoma (NB) is the most common solid, extracranial childhood tumor. "MGMT methylation in the promoter region has also been examined in neuroblastomas as promoter hypermethylation is associated with decreased MGMT expression." (PMID 20924375, 2010). "In neuroblastomas, methylation of several genes, including MGMT, SLIT2, CD44, FLIP and RASSF1A, has been described." (PMID 17064406, 2006). "However, recent evidence suggests that the effectiveness of TMZ in neuroblastomas can be diminished by MGMT-mediated DNA damage repair." (PMID 20924375, 2010). "MGMT is frequently expressed in neuroblastoma tumours and cell lines." (PMID 20924375, 2010). "The purpose of the current study was to assess the activity of the TMZ and irinotecan combination in neuroblastoma pre-clinical models and to determine whether inhibition of MGMT by O6-BG significantly enhanced the anti-tumour activity of the combination." (PMID 20924375, 2010). "Using neuroblastoma pre-clinical models, we determined whether the inhibition of MGMT by O6-benzylguanine (O6-BG) could enhance the anti-tumour activity of TMZ and irinotecan." (PMID 20924375, 2010). "In our study, 10 neuroblastoma cell lines were examined for MGMT RNA and protein expression." (PMID 20924375, 2010). "Thus, MGMT is expressed in neuroblastomas and may be a pharmacological target for therapeutic regimens that include TMZ, as previously suggested." (PMID 20924375, 2010). "Pre-treatment with 25 μM O6-BG sensitised four out of the five tested neuroblastoma cell lines to TMZ by 0.3–1.4 logs; sensitising effect was not demonstrated in the highly drug-resistant CHLA-90 cells that lack MGMT expression." (PMID 20924375, 2010). "It has been hypothesised that the cytotoxic activity of TMZ is mediated through reactive O6-methylguanine in DNA; thus, inhibition of O6-methylguanine-DNA methyltransferase (MGMT), a DNA repair protein at the O6-guanine position, may increase the cytotoxicity of TMZ against neuroblastomas." (PMID 20924375, 2010). "For example, one study reported that exposing GBM cell lines to TMZ in a cyclic manner (3 days of treatment followed by 3 days without drug, repeated twice) resulted in MGMT protein upregulation in SF268 GBM and SK-N-SH neuroblastoma cell lines." (PMID 29930746, 2018). "Next, we examined whether O6-BG can increase the activity of TMZ or the TMZ and irinotecan combination in neuroblastomas using three drug-sensitive (CHLA-15, CHLA-42 and SMS-KCNR) and two multidrug-resistant (CHLA-90 and CHLA-136) cell lines, including the one that does not express MGMT (CHLA-90)." (PMID 20924375, 2010).
neuroendocrine tumors (12 papers, 2009 to 2025). "However, in lung well-differentiated neuroendocrine tumors, despite MGMT being shown to be deficient in approximately 50% of cases, no data are available on a predictive role of MGMT status in chemotherapy-treated patients." (PMID 33641055, 2021). "The expression of MGMT in neuroendocrine tumors (NETs) varies significantly across different anatomical sites." (PMID 39061142, 2024). "In neuroendocrine neoplasms of the lung, pancreas, and other sites, MGMT promoter methylation was reported in 28.4% of the cases studied." (PMID 33287738, 2020). "The influence of MGMT status on alkylating agent sensitivity in patients with neuroendocrine neoplasms (NENs) is controversial." (PMID 32141507, 2020). "Therefore, among the patients with neuroendocrine neoplasms (NENs), MGMT promoter methylation is postulated to be detected more frequently in high grade NENs than low or intermediate grade NENs." (PMID 33287738, 2020). "Therefore, among the patients with neuroendocrine neoplasms (NENs), MGMT promoter methylation could be detected more frequently in high grade NENs than low or intermediate grade NENs." (PMID 33287738, 2020). "Previous studies in Asian samples have shown that MLH1, MGMT, CDKN2A, and RASSF1A genes are hypomethylated in thymomas as compared with thymic carcinomas or neuroendocrine tumors." (PMID 33192293, 2020).
cervical cancer (11 papers, 2005 to 2025). A primary or metastatic malignant neoplasm involving the cervix. "According to the analysis conducted by GEPIA, a significant association was found between downregulated MGMT mRNA expression at the transcriptional level and poor overall survival (p = 0.029, log-rank test) in human cervical cancer." (PMID 37834832, 2023). "Certain studies have found that the abnormal methylation of MGMT was strongly associated with the risk and histological type of cervical cancer." (PMID 37834832, 2023). "Indeed, it was shown that approximately 17% (5–92%) of cervical cancers feature loss of expression of MGMT." (PMID 37834832, 2023). "In cervical cancer, MGMT silencing is a common feature, occurring within an immune environment shaped by genetic variations in cytokine genes." (PMID 40895460, 2025). "The authors utilized The Cancer Genome Atlas (TCGA) database to validate the findings and establish any clinical implications of MGMT methylation in the pathogenesis of cervical cancer." (PMID 37834832, 2023). "Further analysis of TCGA data demonstrated an inverse correlation between MGMT methylation and mRNA expression in cervical cancer." (PMID 37834832, 2023). "To further evaluate this clinically, we utilized MGMT expression and cervical cancer survival data from TCGA." (PMID 37834832, 2023). "Nevertheless, further research is needed to investigate the relationship between the presence and extent of MGMT methylation and the prognosis of cervical pre-cancer and cervical cancer." (PMID 37834832, 2023). "This indicates the potential significance of MGMT methylation as a biomarker for the early detection of cervical cancer." (PMID 37834832, 2023). "Methylation specific-multiplex ligation-dependent probe amplification (MS-MLPA) analysis of cervical carcinomas revealed promoter methylation of 12 out of 29 tumour suppressor genes analysed, with MGMT being most frequently methylated (92%)." (PMID 17971771, 2007). "There is scarce information concerning the role of MGMT gene in cervical cancer; a number of studies have analyzed the frequency of MGMT promoter hypermethylation, which varies from 5–81%." (PMID 16248899, 2005). "In cervical cancer, MGMT promoter methylation has been correlated with radiation sensitivity." (PMID 40895460, 2025). "In this study, we found that the MGMT methylation level could potentially serve as a valuable prognostic indicator for the transition from ASC-US/LSIL to cervical cancer." (PMID 37834832, 2023). "Our findings suggest that the MGMT methylation level could potentially serve as a valuable prognostic indicator for the transition from ASC-US/LSIL to cervical cancer." (PMID 37834832, 2023). "Additionally, we verified the significance of MGMT methylation in the progression of cervical cancer by analyzing public data from TCGA." (PMID 37834832, 2023). "This apparent discrepancy may, at least in part, be explained by heterogeneity of MGMT promoter methylation in cervical carcinomas." (PMID 17971771, 2007). "Although our data could not establish a conclusive association between MGMT methylation and cervical cancer progression because of the small sample size, we attempted to identify any possible correlation using publicly available data from TCGA." (PMID 37834832, 2023). "We can still identify some genes related to cervical cancer progression from the samples of the two patients after treatment, including ATF3, GPX3, IL10, IL6, RAD51AP1, MGMT, WWOX." (PMID 37914994, 2023). "In general, mRNA expression levels are lower in cervical cancer cells lines than in HaCaT cells, except for SOX17 and MYOD1 in SiHa cells, MGMT in C-33A cells and AJAP1, SOX17 and MYOD1 in HeLa cells." (PMID 34991696, 2022). "O-6-methylguanine-DNA methyltransferase (MGMT) is a DNA repair enzyme and has often been found to be methylated in several cancers, including cervical cancer." (PMID 31766427, 2019).
cervical cancer (continued). "The frequency of MGMT methylation as detected by both techniques was different from most previous studies on cervical carcinomas, in which by MSP analysis MGMT methylation frequencies varying from 6.7 to 38% have been reported." (PMID 17971771, 2007). "To confirm MS-MLPA results, we selected the MGMT gene for further analysis, since this gene revealed the highest frequency of positive MS-MLPA test results in cervical carcinoma specimens." (PMID 17971771, 2007). "For example, genes involved in cell cycle (p16), apoptosis (DAPK), cell adherence (CDH1), DNA repair (MGMT), and APC/β-cateninroute (APC) were found to be aberrantly methylated in cervical cancer." (PMID 16928264, 2006). "Incidence of hypermethylation for DAPK, MGMT, p16 and PTEN in cervical cancer was 56.7%, 25.2%, 16.5% and 15.7% respectively." (PMID 16928264, 2006). "TCGA data revealed a significant negative correlation between MGMT methylation levels and mRNA expression in cervical cancer." (PMID 37834832, 2023). "Notably, all eight genes that were frequently methylated in the HPV-transfected cell lines and cervical cancer cell lines (i.e. TP73, ESR1, RARβ, DAPK1, MGMT, CADM1, CDH13 and CHFR) overlapped with those found to be methylated in the cervical carcinoma specimens." (PMID 17971771, 2007).
colorectal tumors (11 papers, 2008 to 2024). "For example, somatic mutations in O6-methylguanine-DNA methyltransferase (MGMT), a protein responsible for removing alkylation at the O-6 position of guanine, have been identified in esophageal and colorectal tumors." (PMID 35048115, 2022). "It is also noteworthy that about 40% of all patients with sporadic CRC display epigenetic inactivation of the DNA repair gene MGMT in colorectal tumors and precursor lesions." (PMID 33978766, 2021). "MGMT promoter methylation and consequently decreased expression is observed in 27-40% of chemo resistant metastatic colorectal tumours and is a frequent event in colorectal carcinogenesis." (PMID 28903334, 2017). "Spearman rank correlations were performed to investigate the correlation of the MLH1 and MGMT methylation levels in patient-matched peripheral blood leukocyte, colorectal tumor and normal colorectal tissue DNA samples." (PMID 24179526, 2013). "Further analysis revealed that a significant difference in MGMT methylation existed between colorectal tumor tissue DNA and leukocytes or normal colorectal tissue DNA (P=0.013 and P=0.035, respectively; χ2 test), but not between leukocyte and normal colorectal tissue DNA (P=0.645; χ2 test)." (PMID 24179526, 2013). "We determined the feasibility of this RMEAM strategy by assessing the methylation density of CpG islands located in the promoter regions of MLH1, TERT and MGMT, and it has been proved that the mathylation of MLH1, TERT and MGMT are associated with carcinogenesis of colorectal tumor." (PMID 18237388, 2008). "Differences in the levels of MGMT and MLH1 methylation were examined in patient-matched peripheral blood leukocyte, colorectal tumor and normal colorectal tissue DNA." (PMID 24179526, 2013). "The present results revealed that the levels of MLH1 and MGMT methylation were not significantly different in patient-matched peripheral blood leukocyte, colorectal tumor tissue and normal colorectal tissue DNA as original semi-quantitatively rank data." (PMID 24179526, 2013).
gliosarcoma (11 papers, 2017 to 2025). A rare histological variant of glioblastoma (WHO grade IV) characterized by a biphasic tissue pattern with alternating areas displaying glial and mesenchymal differentiation (WHO). "In the present study, we determined the methylation status of CpGs in distal MGMT enhancers in samples from 38 IDH-wildtype GBM, one IDH mutated GBM, one gliosarcoma, and for the commercial cell line T98G." (PMID 37371109, 2023). "Samples from 38 IDH-wild-type GBM (GBM01–38), 1 IDH-mutated GBM (GBMm01), and 1 gliosarcoma (GS01) patient and the commercial GBM cell line T98G were subjected to DNA methylation analysis of the MGMT promoter and 4 enhancers by HRM analysis and PSQ." (PMID 37371109, 2023). "MGMT promoter methylation has already been reported for gliosarcoma, but it seems to occur with a lower frequency than in GBM." (PMID 37371109, 2023). "Excluding one patient with unmethylated MGMT disease, all primary gliosarcoma patients diagnosed after 2005 received post-operative radiotherapy and concurrent temozolomide." (PMID 32219069, 2020). "In the gliosarcoma sample analyzed in this study, the MGMT promoter was highly methylated." (PMID 40244270, 2025). "MGMT promoter methylation status of CpGs 72–83 was evaluated using PSQ in 38 patients with GBM (one patient had IDH-mutant GBM, and one patient had gliosarcoma)." (PMID 38521933, 2024). "Patient 8 (imaging not displayed), a 53 year-old man, originally had a right frontal gliosarcoma (IDH1/2 wild type, methylated MGMT promoter)." (PMID 29113409, 2017).
head and neck cancer (11 papers, 2009 to 2024). A primary or metastatic malignant neoplasm affecting the head and neck. "In a meta-analysis based on 20 studies, the promoter of MGMT was hypermethylated in HNSCC compared to healthy controls, suggesting a connection between higher methylation and an increased risk of head and neck cancer." (PMID 31712935, 2020). "Several authors have pointed to a relationship between DNA methylation of tumor suppressor genes such as p16, DAPK and MGMT and the development and progression of head and neck cancers, including oral cancer." (PMID 29454310, 2018). "The methylation array of 4,608 genes (duplicate on chip) that we used in this study included the majority of genes which have previously been associated with head and neck cancer (e.g., DAPK, MGMT, and CDH1, etc.)." (PMID 25197641, 2014). "It is therefore conceivable that as the degree of methylation in head and neck cancers increases, genomic stability declines as a result of decreasing MGMT expression, thus leading to poorer prognosis and tumor recurrence." (PMID 19807915, 2009). "Hypermethylation of promoter regions in head and neck cancer has been shown in many studies, and below we summarize recent studies about p16, PTEN, DAPK, MGMT, ECAD and RASSF1 genes which are frequently analyzed in HNSCC." (PMID 31712935, 2020). "In addition, promoter methylation of CDKN2A, MGMT, DAPK1, and CDH1 has been studied in relation to head and neck cancer survival." (PMID 19807915, 2009).